VDR (vitamin D receptor)
Diseases named in the same sentence as VDR in open-access papers (continued):
Sharing a sentence is not in itself a finding about the gene and the disease.
vitamin D deficiency (continued). "The VDR-regulated furin system we outline is also observed in humans, as we found that ergocalciferol treatment in patients with vitamin D deficiency reduces furin activity and FGF23 cleavage." (PMID 37681408, 2023). "Overall, these studies have demonstrated the impairments induced by vitamin D deficiency or VDR deletion and, conversely, the benefits of high levels of vitamin D supplementation." (PMID 37892452, 2023). "Vitamin D deficiency ultimately contributes to decreased VDR stimulation and decreases VDR expression with age." (PMID 38004107, 2023). "Multiple studies on placental vitamin D metabolism in pregnancy complications demonstrated reduced placental VDR expression, in conjunction with vitamin D deficiency, in preeclampsia, intrauterine growth restriction, and preterm birth." (PMID 36834800, 2023). "We found statistically significant differences in the distribution of rs11168293 genotype variants in the VDR gene between asthma patients with vitamin D deficient (< 20 ng/ml) and asthmatic subjects with vitamin D insufficiency (20–30 ng/ml)." (PMID 37407930, 2023). "Another factor leading to vitamin D deficiency and insufficiency is the role of the intranuclear VDR, which mediates the developmental regulatory effects of vitamin D [1,25(OH)2D3]." (PMID 37513645, 2023). "Several additional studies have reported that VDR polymorphism has an impact on the occurrence of vitamin D deficiency in MM patients." (PMID 37513645, 2023). "Previous studies have shown a link between T2DM and the VDR and have confirmed that vitamin D deficiency can increase the risk of mortality in women with GDM." (PMID 37836571, 2023). "In an animal study with VDR-null mice and rodents, Vitamin D deficiency showed an association with decreased fertility because of impaired sperm production and bad sperm motility." (PMID 37242266, 2023). "Vitamin D deficiency affects the development of dopaminergic neurons in early life, as suggested by an increased vitamin D receptor (VDR) expression in the rat midbrain until weaning, as well as in the human substantia nigra." (PMID 37034443, 2023). "The decreased expression of VDR is the representation of vitamin D deficiency, and the animal model of VDR knockout is also a method for studying vitamin D deficiency." (PMID 36771445, 2023). "In asthma patients with vitamin D deficiency (< 20 ng/ml) the allele G of rs11168293 of VDR was more common than in those having insufficiency (20–30 ng/ml) of vitamin D (63% and 31%, p < 0.05)." (PMID 37407930, 2023). "In vascular smooth muscle cells isolated from vitamin D receptor knockout mice, Angiotensin and Angiotensin II receptor 1 mRNA are significantly upregulated in vitamin D deficiency compared with wild-type mice." (PMID 38068901, 2023). "Weak muscles or altered muscle fibers due to vitamin D deficiency or ablation of vitamin D receptors (VDR)." (PMID 37749664, 2023). "Individuals with hypolactasia and severe serum vitamin D deficiency predominantly had the GA (42.9%) and the AA genotypes (23.8%) of the VDR gene BsmI polymorphism." (PMID 37373338, 2023). "Pericytes express a significantly higher level of VDR thanvascular endothelial cells; therefore, vitamin D deficiency mostly affects thefunctions of the pericytes." (PMID 35170646, 2022). "We assessed the effect of PLD therapy on the reversal of vitamin D deficiency by detecting serum 25(OH)D levels and VDR protein expression in the distal femurs." (PMID 36378815, 2022). "Concomitant GDM and vitamin D deficiency increase placental VDR protein and mRNA levels in placental and umbilical cord blood samples." (PMID 35458211, 2022). "A potential interaction was observed between maternal VDR rs2228570 and maternal vitamin D deficiency on head circumferences." (PMID 35276923, 2022). "There are potential interactions between maternal vitamin D deficiency and maternal VDR rs2228570 and head circumference." (PMID 35276923, 2022).
vitamin D deficiency (continued). "Even with vitamin D deficiency, we observed a higher renal expression (p < 0.01) of VDR in the HFDV group than in the VDD group." (PMID 36466412, 2022). "The discovery of the VDR can lead to a better understanding of the relationship of acute and chronic diseases with vitamin D deficiency." (PMID 36012412, 2022). "It was demonstrated that vitamin D deficiency is associated with severe cirrhosis, and VDR gene polymorphism increases the risk of cirrhosis in PBC and NAFLD patients." (PMID 36142636, 2022). "It has been suggested that vitamin D deficiency increases Iba 1-labeled microglia, and vitamin D receptor activation inhibits microglia-mediated neuroinflammation and oxidative stress." (PMID 36009371, 2022). "This study examined the individual and combined effect of maternal and neonatal vitamin D deficiency and vitamin D-related SNPs (VDR rs2228570, GC rs4588 and GC rs7041) with birth outcomes." (PMID 35276923, 2022). "The discovery of the VDR enabled multiple investigations on the association of vitamin D deficiency with acute and chronic diseases." (PMID 36012412, 2022). "Maternal vitamin D deficiency and cord VDR rs2228570 were significantly associated with birth weight." (PMID 35276923, 2022). "The search strategy used a combination of the following keywords: “vitamin D”, “vitamin D deficiency”, “cholecalciferol”, “vitamin D receptor”, “VDR”, “ergocalciferol”, “pancreatitis”, “chronic pancreatitis”, and “acute pancreatitis”." (PMID 35631254, 2022). "In AIH, PBC or primary sclerosing cholangitis, vitamin D deficiency or VDR from the dendritic cells, and macrophages, seem to be among the important factors in triggering the immune process, the role of VDBP being less studied." (PMID 36142636, 2022). "Previous studies have demonstrated the potential interaction effect between neonatal VDR rs2228570 and maternal GC rs7041 with vitamin D deficiency on birth weight." (PMID 35276923, 2022). "Growing evidence from several preclinical studies in rodents and observational clinical reports suggests that vitamin D deficiency or defective VDR is associated with adverse cardiovascular outcomes." (PMID 35783863, 2022). "Inadequate sun exposure and outdoor activities and changed expression of the vitamin D receptor (VDR) in adipose tissue are likely to be the main causes of the link between obesity and vitamin D insufficiency in obese people." (PMID 36043008, 2022). "The effect of early life vitamin D deficiency on the DNA methylation of Runx2, Osterix, VDR, and RXRA, genes known to play essential roles in bone formation, was assessed." (PMID 35619053, 2022). "Together with other variables, maternal vitamin D deficiency and neonatal VDR rs2228570 explained a 27% birth weight variation." (PMID 35276923, 2022). "The authors pointed out that this decreased expression of VDR and epithelial barrier proteins is the result of vitamin D deficiency." (PMID 36292016, 2022). "This has been demonstrated by studies showing that vitamin D deficiency is associated with pancreatitis and its anti-inflammatory and anti-fibrotic effects by binding with the vitamin D receptor (VDR)." (PMID 35631254, 2022). "Regarding the homocysteine, it was described very recently an interaction between vitamin D deficiency, increased serum homocysteine levels and coronary artery disease via VDR dysfunction." (PMID 35930297, 2022). "Previous data from our group showed that vitamin D deficiency caused a lower renal VDR expression and a higher renal TGF-β1 expression in rats submitted to renal IRI and 5/6 nephrectomy." (PMID 36466412, 2022). "Vitamin D deficiency, low VDR expression, and dysfunction of vitamin D/VDR signaling have been observed in patients with Crohn’s disease (CD) and ulcerative colitis (UC), and they were found to be related to the activity in both diseases." (PMID 36296970, 2022).
vitamin D deficiency (continued). "In this context, vitamin D deficiency is linked with increased hCys in CKD through vascular endothelial cells express VDR and 1α-hydroxylase synthesis." (PMID 35684085, 2022). "Vitamin D deficiency and vitamin D receptor polymorphisms are associated with increased risk of severe viral bronchiolitis in infants." (PMID 32613681, 2021). "Whilst the specific mechanisms whereby vitamin D deficiency contributes to muscle loss are unclear; it is likely that the vitamin D receptor (VDR) plays a role via changes in anabolic signaling, muscle protein synthesis and translational efficacy." (PMID 33671473, 2021). "The aim of this study was to evaluate vitamin D deficiency prevalence and its correlation to RA clinical parameters, and to determine the possible association of VDR gene polymorphisms and RA susceptibility in the Lithuanian population." (PMID 33916688, 2021). "An association between vitamin D deficiency with VDR gene polymorphisms in PCOS and its endocrine-metabolic alterations has been suggested." (PMID 34684492, 2021). "A link between vitamin D receptor (VDR) and muscle protein anabolic signaling has been reported as the mechanism by which vitamin D deficiency is associated with muscle loss." (PMID 34575326, 2021). "Conversely, studies of vitamin D deficiency in humans are assumed to mimic some elements of VDR ablation in mice." (PMID 32904944, 2021). "There is a high prevalence of vitamin D deficiency in elderly populations, and VDR levels decrease in the muscles with advancing age." (PMID 33920130, 2021). "Vitamin D deficiency and defects in activation of VDR have been found to intensify respiratory syndrome in COVID-19 through inducing a wounding response in stellate cells of the respiratory system." (PMID 34147082, 2021). "It has been shown in vivo that vitamin D deficiency leads to reduced vitamin D receptor (VDR) activity and that this inhibits INSIG-2 expression, which in turn releases SREBP to upregulate the mevalonate and Kandutsch–Russell pathways." (PMID 34440777, 2021). "Vitamin D deficiency and VDR deletion are associated with chronic inflammation, partially due to altered M1/M2 polarization." (PMID 34842603, 2021). "VDR has been previously shown to increase the formation and decrease the resorption of bone, and VDR-mediated activity in osteoblasts and osteocytes can prevent bone loss caused by vitamin D deficiency." (PMID 33996619, 2021). "Experimental models with knocked-out VDR exhibited the full phenotypes of severe vitamin D deficiency, indicating that VDR was the major mediator of vitamin D action." (PMID 33924215, 2021). "Whereas vitamin D deficiency adversely affects mitochondrial function by reducing adenosine triphosphate (ATP) production and increasing oxidative stress, as demonstrated in VDR-knockout myoblasts, thus hindering muscle regeneration." (PMID 34684052, 2021). "Regarding vitamin D insufficiency, the VDR rs59128934 G allele was associated with a higher risk of insufficiency." (PMID 34343413, 2021). "The present study analyzed the prevalence of vitamin D deficiency among RA patients and its possible association with RA disease activity and disability scores, as well as the role of VDR polymorphisms and risk of RA." (PMID 33916688, 2021). "Vitamin D deficiency and mutations in the vitamin D receptor (VDR) gene are associated with increased risk of multiple autoimmune diseases, making vitamin D3 therapy a promising candidate." (PMID 33927722, 2021). "Other suggested risk factors for osteoporosis after kidney transplantation are calcium and vitamin D deficiencies, age, female sex, and specific vitamin D receptor (VDR) polymorphisms (BsmI)." (PMID 33306336, 2021). "Many studies have demonstrated that vitamin D deficiency and single-nucleotide polymorphisms in the vitamin D receptor (VDR) impact the immune response." (PMID 34044815, 2021).
vitamin D deficiency (continued). "This COVID-19 complication has been shown to be provoked by vitamin D deficiency and attenuated by induction of the vitamin D receptor (VDR)." (PMID 34147082, 2021). "In a total six variants in the VDR gene have been shown to reduce the risk of vitamin D insufficiency: rs7967152 (A), rs9729(C), rs739837(G), rs11168287(G), rs7963776(G), and rs4237855(G)." (PMID 34343413, 2021). "RA is possibly linked to vitamin D deficiency and vitamin D receptor (VDR) gene polymorphisms, and research demonstrates that FokI variant susceptibility is associated with increased disease risk among Caucasians." (PMID 33916688, 2021). "It was previously reported that vitamin D deficiency and inactivating mutations in vitamin D receptor (VDR) are associated with muscle weakness in humans and mouse models." (PMID 34350631, 2021). "Vitamin D deficiency, as well as VDR knockout, enhances the development and growth of MC-26 colon and breast cancer xenografts in Balb/c mice." (PMID 33732250, 2021). "It has also been indicated that vitamin D deficiency is related to a decrease in the expression of VDR and an altered activity of antioxidant enzymes at the skeletal muscle level." (PMID 32967329, 2020). "Our data suggested that vitamin D treatment raised miR-27a/b expression in oral epithelial cells of mice, whereas vitamin D deficiency or VDR deletion decreased them." (PMID 31942011, 2020). "Vitamin D deficiency has been largely associated with various types of solid and non-solid human cancers, and the almost ubiquitous expression of vitamin D receptor (VDR) has always led to suppose a crucial role of vitamin D in cancer." (PMID 32560347, 2020). "In our present study, the C allele of variant rs9729 on VDR showed to be negatively associated with asthma and vitamin D insufficiency." (PMID 32834827, 2020). "Mice with vitamin D deficiency and global VDR knockout mice showed reduced muscle mass and strength, and muscle decline progressed with age and an increase in the duration of vitamin D deficiency." (PMID 33322706, 2020). "Vitamin D deficiency and vitamin D receptor (VDR) downregulation are associated with inflammatory and autoimmune diseases." (PMID 33088595, 2020). "Both vitamin D deficiency and single nucleotide polymorphisms (SNPs) in the gene encoding the vitamin D receptor (VDR) have been widely reported to associate with susceptibility to polycystic ovarian syndrome (PCOS)." (PMID 32042037, 2020). "Since vitamin D mediates its action by binding to the VDR gene, the suboptimal responsiveness of the VDR can be manifested as vitamin D deficiency." (PMID 32471257, 2020). "Despite numerous relationships between Vitamin D deficiency and loss of-function of VDR and low muscle mass and loss of function, the mechanistic role of VDR overexpression was undefined." (PMID 32771696, 2020). "These clinical and basic research findings indicate that both vitamin D deficiency and decreased VDR levels in muscle tissues are associated with sarcopenia and impaired physical performance." (PMID 33322706, 2020). "The allele C of rs9279 on VDR, was negatively associated with asthma risk (OR = 0.66; 95% CI 0.45–0.97), vitamin D insufficiency (OR = 0.78; 95% CI 0.70–0.96) and higher VDR expression." (PMID 32834827, 2020). "It is known that VDR gene polymorphisms decrease the VDR affinity for vitamin D but in contrast to vitamin D deficiency studies, little is known about the influence of VDR genes on cognition." (PMID 32554862, 2020). "Vitamin D deficiency is inversely correlated with lupus disease activity, and mutations in the vitamin D receptor (VDR) have been identified in SLE populations." (PMID 31978964, 2020). "Vitamin D plays a pivotal role in calcium homeostasis, and either vitamin D deficiency or vitamin D receptor (VDR) mutation/deficiency promotes development of rickets in humans and mice." (PMID 32699341, 2020).
vitamin D deficiency (continued). "Mice knocked-out for the intestine VDR gene and those with vitamin D deficiency, displayed alterations of the tight junctions and increased gut permeability." (PMID 33126575, 2020). "The FokI (rs10735810) polymorphism of the VDR gene was found to be an additional independent determinant of insulin secretion in individuals with vitamin D insufficiency." (PMID 32407388, 2020). "The interaction of plasma renin and vitamin D is tightly connected with the VDR status: in case of vitamin D deficiency there is a reduced transcription of VDR and an enhanced degradation of unliganded VDR, with a decrease in both unliganded and liganded VDR." (PMID 31200589, 2019). "Recently, we have reported that long term of vitamin D deficiency leads to VDR ablation, oxidative stress, and consequence mitochondrial dysfunction, which induces muscle atrophy." (PMID 31281588, 2019). "This study investigated the prevalence of vitamin D deficiency and its association with tumor characteristics and the implications of VDR genetic variations for risk of breast cancer in Ethiopia." (PMID 30699973, 2019). "Taken together, it is very likely that vitamin D deficiency in the long run induces VDR ablation, ROS generation and in consequence deleterious effects on the mitochondrial function, which in turn leads to elevated muscle atrophy." (PMID 30830277, 2019). "It focuses on several aspects related to cellular and molecular physiology such as VDR as the trigger point of vitamin D action, oxidative stress as a consequence of vitamin D deficiency." (PMID 30830277, 2019). "recently published data indicates that vitamin D deficiency is associated with lower VDR content, increased oxidative stress and altered the activity of antioxidant enzymes in skeletal muscle." (PMID 30830277, 2019). "Emerging evidence associates vitamin D deficiency and vitamin D receptor (VDR) genetic variations with risk for breast cancer." (PMID 30699973, 2019). "Some studies have shown associations between vitamin D-binding protein gene polymorphism and the risk of vitamin D deficiency or vitamin-D receptor gene polymorphism and the degree of response to topical vitamin D analogs." (PMID 31139214, 2019). "In particular, there is a great need of a new insight into VDR expression and activation, biogenesis and the function of mitochondria as well as signalling pathways associated with progressive muscle atrophy in vitamin D deficiency." (PMID 30830277, 2019). "Vitamin D deficiency (D-) and VDR deficiency (knockout, KO) exacerbated experimental IBD in multiple models of colitis." (PMID 30723466, 2019). "Vitamin D deficiency has been shown to be able to lead to decrease the concentration of intramyonuclear VDR, VDR gene expression level and contribute to a myopathy caused by type IIA muscle fiber atrophy." (PMID 31382666, 2019). "For example, vitamin D deficiency impacts on neuronal proliferation and differentiation through transcriptional activity, which is mediated by VDR forming a heterodimer with the retinoic acid X receptor and then binding to response elements in the genome." (PMID 31712549, 2019). "Although VDR is predominantly expressed in fast twitch muscles, a study on human paraspinal, slow twice muscle shows that vitamin D deficiency induces its atrophy and decreases the concentration of intramyonucelar VDR and VDR gene expression level." (PMID 30830277, 2019). "Based on this relationship, any impairment of the 1,25(OH)2D3/VDR system (e.g., vitamin D deficiency, VDR polymorphism, or impaired intestinal function) can be assumed to alter the development or progression of colorectal disease." (PMID 30150667, 2018). "The mechanisms underlying this have been well defined in studies examining the development of iNKT cells and the effect of vitamin D deficiency, as well as that of VDR knockout." (PMID 30046564, 2018).